TRPM7 (transient receptor potential cation channel subfamily M member 7)
Diseases named in the same sentence as TRPM7 in open-access papers (continued):
Sharing a sentence is not in itself a finding about the gene and the disease.
glioblastoma (28 papers, 2015 to 2025). The most malignant astrocytic tumor (WHO grade IV). "As for TRPM7, two research works have also demonstrated TRPM7 expression in both glioblastoma and neuroblastoma stem cells, whereas TRPM7 has been linked to stemness promotion and metastasis." (PMID 36142596, 2022). "Functional expression of TRPM7 channels in human glioblastoma cells has been reported by several groups." (PMID 38255793, 2024). "Numerous studies demonstrated the role of TRPM channels, including TRPM7, in the tumorigenesis of glioblastomas." (PMID 38255793, 2024). "A Turkish survey found a significantly higher expression of several TRP channels including TRPM7 in glioblastoma patients." (PMID 38255793, 2024). "The subsequently increased proliferation, migration and invasion of tumor cells were abolished via the knockdown or pharmacological inhibition of TRPM7 in various rodent and human glioblastoma cell lines." (PMID 38255793, 2024). "We had previously reported that TRPM7 promotes glioblastoma proliferation and invasion through the upregulation of FOSL1." (PMID 37642779, 2023). "Recent studies have shown a link between TRPM7 and several cancers such as breast, ovarian, prostate, gastric, bladder, pancreatic cancers, and glioblastomas 52-57." (PMID 35919815, 2022). "TRPM7 expression and activity are not only required for glioma cell proliferation and migration/invasion but also drive glioblastoma stem cells (GSC) plasticity through Notch and STAT3 proliferative activities." (PMID 36844925, 2022). "In glioblastoma cells, high levels of TRPM7 expression were observed compared to the differentiated controls, and its downregulation significantly reduced the stem cell markers CD133 and ALDH1 and inhibited two key stem pathways, STAT3 and Notch." (PMID 36142596, 2022). "Recent studies showed that both prostaglandin E2 (PGE2) and transient receptor potential melastatin 7 (TRPM7) play important roles in migration and proliferation of human glioblastoma cells." (PMID 30338939, 2018). "TRPM7 expression has been shown to be up‐regulated in human glioblastoma, therefore we next studied the effect of PGE2 on the expression of TRPM7 in A172 cells." (PMID 30338939, 2018). "In conclusion, our results demonstrate that PGE2 activates TRPM7 via EP3/PKA signalling pathway, and that PGE2 enhances migration and proliferation of human glioblastoma cells by up‐regulation of the TRPM7 channel." (PMID 30338939, 2018). "This study evaluated the anti-glioblastoma effects of the TRPM7 inhibitor carvacrol on U87 cells and investigated the potential mechanisms underlying these effects." (PMID 25965832, 2015). "In conclusion, carvacrol reduced cell viability, proliferation, migration and invasion in the human glioblastoma U87 cell line, as well as induced apoptosis - likely by inhibiting TRPM7 activity and both the PI3K/Akt and MEK/MAPK signaling pathways." (PMID 25965832, 2015). "In this study, we investigated the effects of the TRPM7 inhibitor carvacrol on the viability, resistance to apoptosis, migration, and invasiveness of the human U87 glioblastoma cell line." (PMID 25965832, 2015). "U87 glioblastoma cells overexpress TRPM7 compared with those in normal astrocytes." (PMID 39857383, 2025). "Moreover, carvacrol treatment inhibits the proliferation and migration of glioblastoma cells by inhibiting the TRPM7-mediated mitogen-activated protein kinase (MAPK) and PI3K/Akt signaling pathways." (PMID 39857383, 2025). "Moreover, TRPM7 in glioblastoma cells has been reported to promote the vesicular transfer of chloride intracellular channel 1 (CLIC1) from glioblastoma to endothelial cells." (PMID 38255793, 2024). "Moreover, the overexpression of TRPM7 has been reported in glioblastoma and in prostatic, nasopharyngeal, pancreatic, breast and ovarian cancers." (PMID 34067290, 2021).
glioblastoma (continued). "We found that PGE2 increased both mRNA and protein expression of TRPM7 in A172 cells, which could partially explain the upregulation of TRPM7 in human glioblastoma." (PMID 30338939, 2018). "Because TRPM7 contributes to the invasiveness of glioblastoma in vitro, antagonism of TRPM7 may prevent tumor metastasis." (PMID 29108231, 2017). "Subsequently, TRPM7 was found to be upregulated in glioblastoma, and inhibition of TRPM7 reduced GBM proliferation, migration, and invasion." (PMID 36768856, 2023). "The transient receptor potential cation channel, subfamily M, member 7 (TRPM7) also leads to increased cancer stem cell proliferation in glioblastoma multiforme (GBM) through activation of the JAK2/STAT3 and/or Notch signaling pathways." (PMID 28219421, 2017). "Therefore, carvacrol may have therapeutic potential for the treatment of glioblastomas through its inhibition of TRPM7 channels." (PMID 25965832, 2015). "Thus, TRPM7 appears to be a promising target for therapeutic intervention in glioblastoma." (PMID 25965832, 2015). "Recent reports have shown that TRPM7 controls proliferation, migration, and invasion of glioblastoma cells and glioma stem cells, suggesting that TRPM7 could potentially serve as a clinical biomarker and therapeutic target for glioblastoma." (PMID 25913706, 2015). "Our previous publication showed that TRPM7 activates STAT3 through the phosphorylation of STAT3 at Tyr705 and increases glioblastoma stemenss; here, we further detected the nuleocytoplasmic distribution of activated STAT3 upon expression of TRPM7." (PMID 37642779, 2023). "We first determined whether TRPM7 is an oncotarget in glioblastoma multiforme (GBM) using the Oncomine database." (PMID 33381038, 2020). "In this study, we found that PGE2 increased TRPM7 currents via EP3/PKA signalling pathway, and that PGE2 enhanced migration and proliferation of human glioblastoma cells by upregulation of TRPM7." (PMID 30338939, 2018). "In the current study, we report that naltriben: 1) potentiates endogenous TRPM7 channel activity and induces Ca2+ influx in the widely used U87 human glioblastoma (GBM) cell line; 2) enhances U87 migration and invasion; and 3) upregulates the MAPK/ERK signaling pathway." (PMID 28061441, 2017). "Several ion channels are involved in regulating the behavior of glioblastoma cells, such as ClC-3, KATP, and TRPM7 channels." (PMID 25913706, 2015). "In this study, we tested the effect of PGE2 on TRPM7 overexpressed in HEK293 cells and endogenous TRPM7 in A172 glioblastoma cells, and whether PGE2 increases proliferation and migration of human glioblastoma cells by stimulation of TRPM7." (PMID 30338939, 2018). "We then tested whether TRPM7 was involved in the stimulatory effect of PGE2 on migration and proliferation of human glioblastoma cells." (PMID 30338939, 2018). "We found that PGE2 increased TRPM7 currents in HEK293 and human glioblastoma A172 cells." (PMID 30338939, 2018). "TRPM7 expression in glioblastoma cells was found to be positively correlated with Notch1 signaling activity and CD133 and ALDH1 expression; briefly, downregulation of TRPM7 by siTRPM7 decreased Notch1 signaling whereas upregulation of TRPM7 increased Notch1 signaling." (PMID 34458247, 2021). "Our findings indicate that TRPM7-regulated PI3K/Akt and MEK/ERK signaling is involved in anti-proliferation and migration effects of xyloketal B on U251 cells, providing in vitro evidence for the marine compound xyloketal B to be a potential drug for treating glioblastoma." (PMID 25913706, 2015). "Therefore, reduced cell viability, proliferation, and cell migration in glioblastoma is caused by suppression of the signaling pathways PI3K/Akt and MEK/ERK as well as by the TRPM7 current blockade without alteration of the TRPM7 protein expression in glioma cells." (PMID 34440090, 2021).
glioma (27 papers, 2015 to 2025). A benign or malignant brain and spinal cord tumor that arises from glial cells (astrocytes, oligodendrocytes, ependymal cells). "TRPM7 is intimately linked to multiple signaling pathways in glioma and has potential as a therapeutic target." (PMID 39633507, 2024). "TRPM7 channel activity is essential for the growth of glioma cells, and its kinase domain is associated with cell migration and invasion." (PMID 39633507, 2024). "We reported previously that TRPM7 is an indirect regulator of the FOSL1 gene where high expression of FOSL1 elevates glioma cell proliferation and invasion; FOSL1 is also associated with poor survival in GBM patients." (PMID 37642779, 2023). "The positive association between increased TRPM7 protein expression and glioma grades strongly indicated that the TRPM7 protein can be used as a diagnostic marker and potential drug target for glioma patients." (PMID 37642779, 2023). "The aim of the present study was to investigate the functional roles of miR-28-5p to elucidate the molecular mechanism of TRPM7's regulation of miR-28-5p in multiple glioma cell lines with different genomic mutational status." (PMID 31921670, 2019). "We conducted an analysis of TRPM7 and NF-κB/p65 protein expression through Western blot and subsequently performed densitometric analysis on triplicated samples of glioma cells using the ImageQuant program." (PMID 38856747, 2024). "A recent publication has revealed that the TRPM7/HOX transcript antisense intergenic RNA axis is overexpressed in glioma cells promoting cell proliferation and invasion." (PMID 38255793, 2024). "For example, carvacrol affects glioma migration, invasion, and proliferation by inhibiting TRPM7 and regulating the G0-G1 cell cycle." (PMID 38680092, 2024). "We have been extensively researching the role of the cation ion channel TRPM7 in glioma initiation and progression." (PMID 38856747, 2024). "In order to better understand how TRPM7 promotes the transcription of the FOSL1 gene to contribute to glioma stemness, we created a FOSL1 promoter and its GAS mutants." (PMID 38791400, 2024). "Knockdown of TRPM7 expression upregulated tumor suppressor miR-28-5p across multiple glioma cell lines." (PMID 36768856, 2023). "Our previous studies have delineated several TRPM7-mediated pathways contributing to the gliomagenesis and glioma stemness." (PMID 37642779, 2023). "TRPM7 was also implicated in the regulation of additional growth pathways, including Notch, STAT3/ALDH1 in glioma cell lines." (PMID 36768856, 2023). "Our previous work demonstrated that TRPM7 induces gliomagenesis and glioma stemness to promote glioma cell survival and invasion, where one of the mechanisms is through regulating its downstream Notch 1/Survivin pathway." (PMID 37642779, 2023). "TRPM7 is notable for its differential regulation of glioma behavior through two distinct modalities." (PMID 36768856, 2023). "We further examined GSC markers ALDH1 and TRPM7 as well as FOSL1 by immunohistochemistry staining (IHC) in brain tissue microarray (TMA) of glioma patients." (PMID 37642779, 2023). "These interactions prompted us to investigate the mechanism by which TRPM7 modulates FOSL1 transcriptional activation in glioma cell." (PMID 37642779, 2023). "Our present study discovered a novel signaling pathway of TRPM7/STAT3/FOSL1 axis that leads to glioma aggressiveness through stemness, suggesting novel therapeutic opportunities for the malignant disease." (PMID 37642779, 2023). "TRPM7 activates the JAK2/STAT3 signaling pathway leading to glioma aggravation, as there is crosstalk between this pathway and ALDH1 and CD133, two glioma stemness markers, suggesting a role of TRPM7 in glioma stem cells." (PMID 37762011, 2023). "In the current study, we investigated the role of TRPM7/STAT3/FOSL1 axis in promoting glioma stemness and gliomagenesis." (PMID 37642779, 2023).
glioma (continued). "In contrast, TRPM7 suppresses glioma progression through miR-28-5p regulation in GBM cells with subsequent effects on cell proliferation and invasion." (PMID 35625048, 2022). "Lidocaine inhibited glioma cell proliferation and metastasis via the blockade of TRPM7 channels, which prevented the cell cycle and induced protective autophagy." (PMID 34950031, 2021). "Local anesthetic (e.g., lidocaine) upregulates the TRPV1 channels and suppresses the TRPM7 channels, and both of these mechanisms protect against glioma cell proliferation." (PMID 34389754, 2021). "This has to be put into the context that TRPM7 channel exhibits an intrinsic kinase activity, thus supporting that TRPM7 effects on glioma cell growth are mediated by its channel activity while cell migration and invasion required its kinase domain." (PMID 33928077, 2021). "Four TRP melastatin subfamily members, TRPM2, TRPM3, TRPM7, and TRPM8, have been implicated in glioma cell growth, proliferation and migration." (PMID 33928077, 2021). "TRPM7 also controls glioma progression through miRNA regulation in GBM cells with subsequent effects on cell proliferation and invasion." (PMID 33928077, 2021). "Pharmacological inhibition or siRNA for TRPM7 also reduces migration and invasion in human glioma cells and antagonist for TRPM7 reduces various cellular functions such as proliferation, viability, migration, and invasion in both U251/U87 cells." (PMID 34149360, 2021). "The discovery of different cellular and molecular targets affecting gliomas development and progression through their modulation by TRPM7 provides key insights for the development of novel therapeutic agents for glioma treatments." (PMID 33928077, 2021). "Lidocaine prevented the cell cycle and induced protective autophagy in glioma cells by blocking TRPM7 channels." (PMID 34950031, 2021). "This can be connected with the role of TRPM7 on cell proliferation, migration and invasion in glioma cells and GSCs through the upregulation of JAK2/STAT3 and/or Notch signaling pathways." (PMID 33928077, 2021). "TRPM7 silencing reduced glioma cell growth by inhibiting cell entry into S and G2/M phases and promoting cell apoptosis." (PMID 33381038, 2020). "Among brain tumors, our research group pioneered TRPM7's oncogenic function in glioma proliferation, invasion, and glioma stemness." (PMID 33381038, 2020). "Given this, we expect that the Notch1 signaling blockade will reverse the effects of TRPM7 on glioma proliferation." (PMID 33381038, 2020). "Lastly, we determined the changes in TRPM7-mediated regulation of glioma cell growth/proliferation, cell cycle, and apoptosis by targeting Notch1." (PMID 33381038, 2020). "A172 and U87MG glioma cells were treated with siNotch1 along with TRPM7 wild-type constructs for 72 h, followed by Annexin V and 7AAD binding assay." (PMID 33381038, 2020). "A meta-analysis of microarray gene expression data sets related to human cancer genes revealed that TRPM7 mRNA is highly expressed in glioma patients' tumor tissues compared to that in normal brain tissues." (PMID 33381038, 2020). "We have reported that transient receptor potential melastatin-related 7 (TRPM7) regulates glioma stem cells (GSC) growth and proliferation through Notch, STAT3-ALDH1, and CD133 signaling pathways." (PMID 33381038, 2020). "Our previous report showed that in human glioma cells, TRPM7 expression is upregulated, required for proliferation, migration, and invasion, and mediated by multiple mechanisms through Notch, STAT3-ALDH1, and CD133 signaling pathways." (PMID 33381038, 2020). "To further explore the mechanism that TRPM7 regulates Notch signaling pathway in the tumorigenesis of glioma, we examined all Notch receptor expressions in response to TRPM7 silencing in various glioma cell lines." (PMID 33381038, 2020). "In this study, we determined the major contributor(s) to TRPM7 mediated glioma stemness by further deciphering each individual Notch signaling." (PMID 33381038, 2020).
glioma (continued). "In the current study, we first show that TRPM7-mediated Notch1 signaling activation is a crucial contributor to glioma cell proliferation and GSC stemness." (PMID 33381038, 2020). "As supported by our data above, Notch1 acts downstream to TRPM7 and contribute to the malignancy of glioma." (PMID 33381038, 2020). "TRPM7 increases the growth and proliferation of glioma cells through unlocking G1/S arrests, stimulating cell entry into S and G2/M phases, and inhibiting glioma cell apoptosis." (PMID 33381038, 2020). "Our data suggest that the downregulation of TRPM7 suppresses glioma proliferation by G0/G1 phase arrest concomitant with apoptosis induction." (PMID 33381038, 2020). "Silencing of Notch1 can revert the effects of TRPM7 on cell cycle and programmed cell death in glioma cells, which indicates that Notch1 can replace the TRPM7 function, or TRPM7 functions through Notch1 signaling pathway." (PMID 33381038, 2020). "We have reported that the activation of TRPM7 channels plays an important role in the growth and proliferation of human glioma cells." (PMID 31921670, 2019). "Cell invasion was significantly reduced in two TRPM7 mutants with inactive kinase domain, Δkinase, and K1648R transfected glioma cells." (PMID 31921670, 2019). "TRPM7 regulates miR-28-5p expression, which suppresses cell proliferation and invasion in glioma cells by targeting Rap1b signaling." (PMID 31921670, 2019). "To seal the gap between TRPM7 and miRNA in the existing literature, we determined the changes in miRNA in response to reduced TRPM7 expression in glioma cells." (PMID 31921670, 2019). "The effects of TRPM7 on glioma cell proliferation and invasion were determined using MTT assays and transwell invasion assays, respectively." (PMID 31921670, 2019). "Our results showed that miR-28-5p inhibits glioma cell proliferation and invasion by targeting its downstream Rap1b gene, and miR-28-5p is regulated by TRPM7." (PMID 31921670, 2019). "Our in-depth data analysis from miRNA microarray data revealed a list of 16 downregulated and 10 upregulated miRNAs whose transcripts are statistically significant with fold changes >2 by TRPM7 knock-down in A172 glioma cells." (PMID 31921670, 2019). "Our results suggest that miRNA changes demonstrate different glioma tumorigenicity, and miR-26b-5p, miR-4530, and miR-28-5p are regulated by TRPM7 and participate in glioma progression." (PMID 31921670, 2019). "In our approach to test the involvement of TRPM7, we quantified its expression by quantitative real-time PCR (qPCR) in glioma cell lines (#12537-GB, U-87) as well as in DPSCs." (PMID 28410232, 2017). "Accordingly, all cell lines expressed TRPM7, but expression in glioma cell lines (#12537-GB, U-87) was stronger than in dental stem cells (DPSCs)." (PMID 28410232, 2017). "Silencing of TRPM7 has been previously shown to reduce cell viability, migration, and invasion of A172 cells- a human glioma cell line." (PMID 25965832, 2015). "Recent studies have focused on the TRPM7 pathway in glioma cells and stem-like cells derived from human glioma cell lines." (PMID 25965832, 2015). "Tumor recurrence is attributed to migration, invasion, and resistance to therapy, and pharmacological inhibition of TRPM7 may be a novel therapy in glioma." (PMID 38680092, 2024). "Specifically, TRPM2 and TRPM3 demonstrate anti-tumor effects in gliomas, while TRPM7 and TRPM8 may play a role in the malignant transformation of gliomas." (PMID 39633507, 2024). "TRPM7 (transient receptor potential cation channel subfamily M member 7) facilitates the transport of calcium ions, and its pharmacological inhibition decreases the proliferation, migration, and invasion of glioma cells." (PMID 39001551, 2024). "Our earlier work indicated that TRPM7 controls the stemness of glioma cells by influencing STAT3." (PMID 38791400, 2024).